ICAM1 (intercellular adhesion molecule 1)
Diseases named in the same sentence as ICAM1 in open-access papers (continued):
Sharing a sentence is not in itself a finding about the gene and the disease.
lung carcinoma (continued). "Also ICAM1, which also showed an equal abundance in lung cancer and controls in our study, was previously discussed as important for lung cancer." (PMID 26930711, 2016). "Noteworthy, lymphocyte function associated antigen 1 (LFA-1), the cognate ICAM-1 receptor on the surface of immune cells, has recently been demonstrated to confer LAK cell-mediated killing of lung cancer cells incubated with the ICAM-1-upregulating phytocannabinoid cannabidiol before." (PMID 26513172, 2015). "In comparison, the same concentration of celecoxib tested under comparable experimental conditions resulted in an upregulation of ICAM-1 protein level in lung cancer cells (A549, H460, lung cancer patient's metastatic cells) by up to 3.7-, 8- or 6.3-fold over control." (PMID 26513172, 2015). "In a lung cancer model, the enhancement of brain metastasis by inflammatory conditions was shown to involve VCAM-1 and ICAM-1 on brain endothelium, but inflammation did not enhance lung cancer cell adhesion to and extravasation from brain vessels or brain metastasis in icam-1 deficient mice." (PMID 37173970, 2023). "Interestingly, lower ICAM1 levels also indicated poor prognoses in lung cancer patients." (PMID 32195055, 2020). "Using lung cancer cell lines (A549, H460) and metastatic cells derived from a lung cancer patient, the present study investigates the impact of celecoxib on the expression of intercellular adhesion molecule 1 (ICAM-1) and cancer cell lysis by lymphokine-activated killer (LAK) cells." (PMID 26513172, 2015). "However, in contrast to lung cancer cells celecoxib neither significantly affected ICAM-1 protein expression nor susceptibility of these cells against LAK cell-induced cytotoxicity." (PMID 26513172, 2015). "Since the upregulation effects of Au-NPs on MMP-9 and ICAM-1 expression in A549 and 95D cell suggested that small particles might possess the ability to facilitate the invasion of lung cancer cells, further in vivo studies are required to confirm the mechanisms." (PMID 24901215, 2014). "CDK4/6 inhibitors can trigger ICAM1 to coordinate anti-tumor immune responses and make LKB1 mutant lung cancer sensitive to immunotherapy." (PMID 40568576, 2025). "Blocking ICAM-1–FGG interaction disrupts the survival signaling and activates caspase-9/3, thus inducing cancer cell apoptosis and prevents lung cancer progression in vivo." (PMID 39168965, 2024). "Tetrandrine (Tet) can inhibit lung cancer cell proliferation, induce apoptosis, and suppress lung cancer growth by destructing the VEGF/HIF-1α/ICAM-1 signaling pathway." (PMID 38136352, 2023). "Endothelial cells express intercellular adhesion molecule 1 (ICAM-1) and VCAM-1, which are important in the attachment between cancer cells and the endothelial cells, as demonstrated on a lung cancer model." (PMID 36835266, 2023). "Here the authors show that Lkb1-deficient lung tumors are characterized by defective trafficking and adhesion of T cells and that, by upregulating ICAM1 expression, CDK4/6 inhibitors sensitize LKB1 mutant lung cancer to anti-PD1 blockade." (PMID 36871040, 2023). "Higher levels of Tenascin C (TNC), ICAM1, and VEGFA further supported that they were involved in pleural metastasis in lung cancer." (PMID 37649596, 2023). "In conclusion, we validated that RT suppressed lung cancer and overexpress PD-L1, CXCL10, and ICAM-1, which exhibited different roles in regulating CD8+ T cell activity." (PMID 36688994, 2023). "Authors achieved a significant reduction in PGE2 and ICAM-1 expression levels, as well as a reduction in STAT-3 phosphorylation levels by inhibiting sPLA2 in lung cancer cells." (PMID 34208346, 2021). "To further assess the expression of ICAM1 and HELLS, we measured mRNA levels in 79 cases of lung cancer and paired paracancer samples." (PMID 32195055, 2020).
lung carcinoma (continued). "Therefore, ICAM1 may be a novel potential therapy target for lung cancer patients." (PMID 32195055, 2020). "In our study, we found that ICAM-1 knockdown regulated the phosphorylation of SHP-2, Akt, JNK and p38 in NSCLC cells, suggesting a crosstalk between ICAM-1 and intracellular signaling cascades that orchestrates the lung cancer cell survival signals." (PMID 39168965, 2024). "A dose of 500 mg/kg/day orally for 20 weeks exhibited recovery effects on NNK-induced lung cancer with a good safety margin, where Intercellular Adhesion Molecule-1 (ICAM-1), the lung cancer biomarker, was significantly reduced by about 18.75% compared to cancer control." (PMID 39684736, 2024). "Therefore, we investigated the expression of PD-L1, ICAM-1, CXCL10, and IFNs-mediated ISG15 expression in patients with lung cancer (LUAD), liver cancer (LIHC), and colorectal cancer (COAD) using the available GEPIA based on the TCGA database." (PMID 38953994, 2024). "AXL could affect cytotoxic immune response against tumors by reducing the expression of intercellular adhesion molecule 1 (ICAM1) and UL16 binding protein 1 (ULBP1) in mesenchymal human lung cancer cells." (PMID 37328828, 2023). "Lymphocyte-EC interactions with respect to lymphocyte recruitment and homing pathways, such as ICAM1/2-integrin and HAS2/MMP7-CD44, were enriched in early stages of lung cancer nodules compared to advanced lung cancer, indicating that EC remodels lymphocytes in the direction of immunosuppression." (PMID 37187731, 2023). "In vitro, investigations using lung cancer cell lines A549, H358, and H460 showed that CBD upregulated the antimetastatic protein ICAM-1, which is hypothesized to reduce tumor development through an immunosurveillance mechanism." (PMID 37397476, 2023). "In a study using lung cancer cell lines, including A549, H358, and H460 NSCLC, low doses of CBD (up to 3 μM) significantly attenuated intercellular adhesion molecule-1 (ICAM-1)-dependent cell invasion via cannabinoid receptors, TRPV1, and p42/44 mitogen-activated protein kinase (MAPK)." (PMID 35741337, 2022). "Interestingly, knockout of ICAM1 (KO-ICAM1) with CRISPR technology in lung cancer cells (i.e., A549, H1299, and CL1-0) ultimately diminished the potentiation effects of DAC for γδ T cell killing in all three cell lines tested." (PMID 33846331, 2021). "As anticipated, DAC treatment of ICAM1-knockout cells failed to enhance immune synapse formation between lung cancer and γδ T cells." (PMID 33846331, 2021). "If LFA-1 engagement by ICAM-1 is sufficient to activate iNKT cells in this model of lung cancer/Vγ9Vδ2 T, interactions of adhesion molecules are not sufficient to induce an activating signaling in Vγ9Vδ2 T cells." (PMID 32733462, 2020). "In this study, we found that Apatinib could inhibit the expressions of stemness biomarkers ABCG2, CD24, ICAM-1, OCT4, and SOX2 in lung cancer." (PMID 32849930, 2020). "In conclusion, we used integrated bioinformatics analysis to identify candidate genes and pathways in lung cancer to show that HELLS and ICAM1 might be the key genes related to tumorigenesis or tumor progression in lung cancer." (PMID 32195055, 2020). "Collectively, the present study identified upregulation of ICAM-1 expression in lung cancer cells leading to LAK cell-mediated tumor cell lysis as a novel antitumorigenic mechanism of celecoxib." (PMID 26513172, 2015). "In the present study upregulation of ICAM-1 protein expression in lung cancer cells was confined to celecoxib and was not elicited by other related selective COX-2 inhibitors (i." (PMID 26513172, 2015).
lung carcinoma (continued). "According to the real-time PCR detection results, for the surface marker-related genes of lung cancer stem cells, the expressions of CD13 and CD44 were upregulated in the Apatinib group when compared to the control group, whereas the expressions of ABCG2, CD24, and ICAM-1 were downregulated." (PMID 32849930, 2020). "Helicase, Lymphoid-Specific (HELLS) and Intercellular adhesion molecule 1 (ICAM1) were identified, and their biological functions and key pathways were enriched to ascertain more accurate and practical biomarkers for the early diagnosis, individualized prevention, and treatment of lung cancer." (PMID 32195055, 2020). "In addition, we performed γδ TCR and NKG2D blocking assays to determine whether DAC-mediated ICAM-1 upregulation may override the conventional tumor recognition mechanisms through γδ TCR or NKG2D at the interface between γδ T cells and DAC-pretreated lung cancer cells." (PMID 33846331, 2021). "However, ICAM-1 Lys8-Ser22 peptide failed to induce NSCLC cell apoptosis (data not shown), probably due to excess autocrine FGG secreted by lung cancer cells which cannot been fully neutralized by the peptide." (PMID 39168965, 2024).
Hyperglycemia (87 papers, 2006 to 2025). An increased concentration of glucose in the blood. "In uninjured corneas of wild-type mice, hyperglycemia upregulated the expression of IL-1β, IL-1Ra, and ICAM1, whereas IL-36R deficiency attenuated this increase." (PMID 37371057, 2023). "Nuclear translocation of NF-κB (phosphorylation of p65 subunit) in endothelial cells caused by hyperglycemia and oxidative stress has been linked to transcriptional activation of adhesion molecules like ICAM-1." (PMID 24040012, 2013). "Endothelial cell activation, elevated intercellular adhesion molecules, and enhanced intercellular adhesion in patients with hyperglycemia may be implicated in abnormal ICAM-1." (PMID 38084239, 2023). "Interestingly, in the T2D patients under treatment (but still with hyperglycemia) we observed increased levels of ICAM-1, VCAM-1 and IL-8 in PBMCs associated to ROCK activation whereas their circulating of both IL-6 and IL-8 were similar to controls." (PMID 32375786, 2020). "Previous studies have suggested that hyperglycemia may cause ICAM-1 increases through the activation of IL-1β and the p38 MAPK pathway." (PMID 25389378, 2014). "It has been shown to counter the effect of hyperglycemia and enhance glycocalyx density and thickness in association with the effect on glycocalyx function and reduction of hyperglycemia-induced endothelial cell surface adhesion molecules E-selectin and intracellular adhesion molecule-1 (ICAM-1)." (PMID 37233179, 2023). "Acute and persistent hyperglycemia increases intercellular adhesion molecule-1 levels and other inflammatory molecules (tumor necrosis factor-α, CRP), which would augment plugging of platelets and leukocytes in the capillaries." (PMID 40863381, 2025). "Specifically, DAPA can inhibit hyperglycemia-induced upregulation of intercellular adhesion molecule-1 (ICAM-1), while EMPA inhibits certain chemokines such as monocyte chemoattractant protein-1 (MCP-1)." (PMID 41164749, 2025). "Elevated 8‐OHdG, Ox‐LDL, and ICAM‐1 levels in normoglycemic offspring suggest that these metabolic alterations emerge well before overt hyperglycemia." (PMID 40739796, 2025). "The possible mechanisms are as follows: Acute hyperglycemia also increases the levels of intercellular adhesion molecule-1 and P-selectin, which in turn enhance the lodging of leukocytes in the capillaries." (PMID 38802898, 2024). "In vitro studies have demonstrated the dapagliflozin-mediated attenuation of TNF-α- and hyperglycemia-induced increases in ICAM-1, VCAM-1, PAI-1 and nuclear factor-kappa B (NFκB) expression." (PMID 37367894, 2023). "Hyperglycemia decreases the expression of ICAM-1 and affects low proliferation of endothelial cells." (PMID 37822716, 2023). "First, hyperglycemia will aggravate leukocyte blockage in microcirculation, and acute hyperglycemia will increase the level of intercellular adhesion molecule-1 or P-selectin." (PMID 35308062, 2022). "First, hyperglycemia increases the level of intercellular adhesion molecule-1 (ICAM-1) and P-selectin that increases the adhesion of leukocytes to capillaries with increasing the obstruction of the capillary bed." (PMID 35586740, 2022). "Persistent hyperglycemia activates NF-κB, which increases the expression of various adhesion molecules and proinflammatory cytokines (i.e., ICAM-1, MCP-1, IL-1β, and IL-6)." (PMID 34281287, 2021). "The increase in macrophages is also associated with upregulated ICAM-1 and MCP-1 by kidney tubular cells in response to hyperglycemia and advanced glycation end products (AGEs)." (PMID 34424825, 2021). "The potential mechanism suggested that the increase in the ICAM1 levels may cause vascular endothelial dysfunction, leading to vascular inflammation, vascular functional imbalance, and increased oxidative stress, thus promoting the progression of hyperglycemia." (PMID 35046894, 2021).
Hyperglycemia (continued). "Under a diabetic condition with hyperglycemia, the ICAM1 gene transcription in the nuclei is increased and expression on the surface of endothelium cells is upregulated." (PMID 32626783, 2020). "In a study of diabetic retinopathy induced by hyperglycemia, the transcript and protein levels of ICAM1 were upregulated." (PMID 33115500, 2020). "Hyperglycemia leads to upregulation of intercellular adhesion molecule 1 (ICAM-1), which mediates leukocyte adhesion to the vascular endothelium, resulting in vascular damage and capillary nonperfusion." (PMID 31930145, 2019). "Compared to the normoglycemic ischemic group, hyperglycemia increased the expression of ICAM-1 mRNA at 3 and 6 days of reperfusion." (PMID 25389378, 2014). "Compared to the normoglycemic animals, hyperglycemia significantly increased the ICAM-1 protein levels at 3 and 6 days of reperfusion in the frontal cortex." (PMID 25389378, 2014). "ICAM-1 expression is increased in models of type 1 and 2 diabetes and can be induced by hyperglycemia, advanced glycosylation end products, oxidative stress, hyperlipidemia, hyperinsulinemia, and proinflammatory cytokines." (PMID 24027593, 2013). "Activation of renal endothelial cell ICAM-1 expression by hyperglycemia and subsequent leukocyte infiltration has been suggested to be an important event in pathophysiology of inflammation in DN." (PMID 24040012, 2013). "In a diabetic condition with hyperglycemia, the ICAM1 gene transcription in the nuclei is increased and the ICAM1 gene expression on the surface of endothelium cells is up-regulated." (PMID 23346076, 2012). "We investigated if citrate treatment of endothelial cells during conditions of hyperglycaemia affects ICAM-1 and VCAM-1." (PMID 22045866, 2012). "Citrate treatment decreased both hyperglycaemia-induced ICAM-1 expression and hyperglycaemia-induced neutrophil diapedesis." (PMID 22045866, 2012). "Other mechanisms of cell injury by hyperglycaemia include higher inflammatory response, higher circulating intercellular adhesion molecule (ICAM)-1 and increased production of superoxide radicals and other reactive oxygen species by oxidative stress." (PMID 22553938, 2012). "ICAM-1, upregulated during inflammation and hyperglycemia, is involved in the attachment of lymphocytes to the endothelium as well as in the priming of effector T cells." (PMID 18045485, 2007). "Moreover, GSNO treatment also normalized the level of hyperglycemia-induced expression of inflammatory adhesion molecule, Intercellular Adhesion Molecule-1 (ICAM1) in both cultured EC and rat aorta." (PMID 40289112, 2025). "First, hyperglycemia is known to stimulate the proinflammatory transcription factors, such as nuclear factor κB, increase the expression of intercellular adhesion molecule‐1 (ICAM‐1) and neutrophil infiltration and lead to ischemic tissue damage." (PMID 32697441, 2020). "In our study, an acute increase in PG could increase the plasma levels of IL-6, TNF-α and ICAM-1 and their expression by vascular endothelial cells, and greater inductions were observed following exposure to fluctuant hyperglycemia." (PMID 27496150, 2016). "It is known that hyperglycemia upregulates ICAM-1 in vascular endothelial cells." (PMID 25389378, 2014). "The results revealed that diabetic hyperglycemia further increased the mRNA and protein levels of ICAM-1 in the frontal cortex after 1–6 days compared with the normoglycemic ischemic animals, suggesting that hyperglycemia aggravates ischemia-induced inflammation." (PMID 25389378, 2014). "ICAM-1 mRNA and protein of ICAM-1 were reported to be increased by hyperglycaemia." (PMID 16978373, 2006). "Hyperglycemia and dyslipidemia also promote monocyte adhesion to endothelial cells by inhibiting nitric oxide production and increasing levels of endothelin-1, E-selectin, intercellular adhesion molecule 1 (ICAM-1) and VCAM-1, ROS, angiotensin II, and a plasminogen activator inhibitor." (PMID 35625904, 2022).